AGTR1 (angiotensin II receptor type 1)
Description:
Receptor for angiotensin II, a vasoconstricting peptide, which acts as a key regulator of blood pressure and sodium retention by the kidney. The activated receptor in turn couples to G-alpha proteins G(q) (GNAQ, GNA11, GNA14 or GNA15) and thus activates phospholipase C and increases the cytosolic Ca(2+) concentrations, which in turn triggers cellular responses such as stimulation of protein kinase C. (Microbial infection) During SARS coronavirus-2/SARS-CoV-2 infection, it is able to recognize and internalize the complex formed by secreted ACE2 and SARS-CoV-2 spike protein through DNM2/dynamin 2-dependent endocytosis.
Synonyms: AGTR1A; AGTR1B; AT2R1; AT2R1B; AT1; AT2R1A; HAT1R; AG2S; AT1B; ATR1; AT1AR; AT1BR; AT1R
Tractability: Small molecule: an approved drug acts on it; a structure with a bound ligand is known; a high-quality ligand is known; it belongs to a druggable protein family. Antibody: UniProt places it where antibodies can reach, with high confidence; its Gene Ontology location is reachable by antibodies, with high confidence; UniProt predicts a signal peptide or a membrane-spanning region. PROTAC: ubiquitination databases record sites on it; a small molecule that binds it is known. Other modalities: an approved drug acts on it.
Target class: Membrane receptor; Angiotensin receptor; Peptide receptor (family A GPCR); Family A G protein-coupled receptor; Short peptide receptor (family A GPCR)
Safety:
Unwanted effects reported when the protein is acted on. In parentheses: how it was acted on, where the effect was seen, and who reports it.
antihypertensive and cardioprotective agent (inhibition; cardiovascular system; source: Urban et al. (2012))
cell proliferation and migration (activation; cardiovascular system; source: Urban et al. (2012))
cerebral complications (inhibition, developmental toxicity; renal, cardiovascular; source: Lynch et al. (2017))
death (inhibition, developmental toxicity; renal, cardiovascular; source: Lynch et al. (2017))
decreased blood pressure (inhibition, acute dosing, developmental toxicity; renal, cardiovascular; source: Lynch et al. (2017))
decreased pain (inhibition, acute dosing; renal, cardiovascular; source: Lynch et al. (2017))
decreased urinary sodium excretion (activation, acute dosing; renal, cardiovascular; source: Lynch et al. (2017))
dizziness (inhibition; cardiovascular system; source: Urban et al. (2012))
dry mouth (inhibition; cardiovascular system; source: Urban et al. (2012))
excessive thirst (inhibition; cardiovascular system; source: Urban et al. (2012))
hypocalvaria (inhibition, developmental toxicity; renal, cardiovascular; source: Lynch et al. (2017))
hypotension (inhibition; cardiovascular system; source: Urban et al. (2012))
increased blood pressure (activation, acute dosing; renal, cardiovascular; source: Lynch et al. (2017))
increased pain (activation, acute dosing; renal, cardiovascular; source: Lynch et al. (2017))
increased/decreased urinary sodium excretion (inhibition, acute dosing; renal, cardiovascular; source: Lynch et al. (2017))
increased/decreased urine excretion (inhibition, acute dosing; renal, cardiovascular; source: Lynch et al. (2017))
intrauterine growth retardation (inhibition, developmental toxicity; renal, cardiovascular; source: Lynch et al. (2017))
limb defects (inhibition, developmental toxicity; renal, cardiovascular; source: Lynch et al. (2017))
oligoamnios (inhibition, developmental toxicity; renal, cardiovascular; source: Lynch et al. (2017))
persistent patent ductus arteriosus (inhibition, developmental toxicity; renal, cardiovascular; source: Lynch et al. (2017))
positive inotropy (activation; cardiovascular system; source: Urban et al. (2012))
pulmonary hypoplasia (inhibition, developmental toxicity; renal, cardiovascular; source: Lynch et al. (2017))
renal failure (inhibition, developmental toxicity; renal, cardiovascular; source: Lynch et al. (2017))
respiratory distress syndrome (inhibition, developmental toxicity; renal, cardiovascular; source: Lynch et al. (2017))
slow or irregular heartbeat (inhibition; cardiovascular system; source: Urban et al. (2012))
vasocontriction (activation; cardiovascular system; source: Urban et al. (2012))
diabetes mellitus (source: ClinPGx)
major cardiovascular events rate (source: ClinPGx)
Myocardial Infarction (source: ClinPGx)
Gene: Protein-coding gene on chromosome 3 (148,697,784 to 148,743,045, forward strand). Ensembl gene ENSG00000144891.
Subcellular location: Cell membrane
Subcellular location (Human Protein Atlas): Vesicles
Pathways (Reactome):
Signal Transduction: G alpha (q) signalling events; Peptide ligand-binding receptors
Vesicle-mediated transport: Cargo recognition for clathrin-mediated endocytosis; Clathrin-mediated endocytosis
Gene Ontology:
Molecular function: angiotensin type I receptor activity; angiotensin type II receptor activity; bradykinin receptor binding; protein binding; protein heterodimerization activity; G protein-coupled receptor activity
Biological process: angiotensin-activated signaling pathway; calcium-mediated signaling; cell chemotaxis; G protein-coupled receptor signaling pathway; kidney development; maintenance of blood vessel diameter homeostasis by renin-angiotensin; phospholipase C-activating angiotensin-activated signaling pathway; phospholipase C-activating G protein-coupled receptor signaling pathway; positive regulation of blood vessel endothelial cell proliferation involved in sprouting angiogenesis; positive regulation of cholesterol metabolic process; positive regulation of cytosolic calcium ion concentration; positive regulation of macrophage derived foam cell differentiation; regulation of vasoconstriction; Rho protein signal transduction; symbiont entry into host cell; blood vessel diameter maintenance; inflammatory response; low-density lipoprotein particle remodeling; positive regulation of inflammatory response; positive regulation of reactive oxygen species metabolic process; regulation of blood pressure; regulation of cell growth; regulation of cell population proliferation; regulation of inflammatory response; regulation of renal sodium excretion; and 2 more
Cellular component: plasma membrane; membrane
Genetic constraint (gnomAD): Loss-of-function variants: 16 observed, 21.83 expected, observed/expected ratio (o/e) 0.73, 90% interval 0.5 to 1.11. The upper end of that interval is the gene's LOEUF score, 1.11, which puts it in group 4 of 6, group 1 being the genes least tolerant of losing a copy. Missense variants: 373 observed, 453.19 expected, observed/expected ratio (o/e) 0.82, 90% interval 0.75 to 0.9. Synonymous variants: 153 observed, 164.13 expected, observed/expected ratio (o/e) 0.93, 90% interval 0.82 to 1.07.
Homologues: Orthologues: chimpanzee AGTR1 (99% identical), macaque AGTR1 (99% identical), rabbit AGTR1 (98% identical), pig AGTR1 (96% identical), guinea pig AGTR1 (96% identical), dog AGTR1 (95% identical), rat Agtr1a (95% identical), mouse Agtr1a (94% identical), rat Agtr1b (94% identical), mouse Agtr1b (93% identical), tropical clawed frog agtr1 (62% identical), zebrafish agtr1a (47% identical), and 1 more. Paralogues in human: AGTR2 (31% identical), APLNR (30% identical), GPR25 (28% identical), BDKRB1 (28% identical), BDKRB2 (27% identical), GPR15 (26% identical), RXFP4 (23% identical).
Diseases named in the same sentence as AGTR1 in open-access papers:
AGTR1 is named in the same sentence as 443 diseases in open-access papers, as found by Europe PMC text mining. Sharing a sentence is not in itself a finding about the gene and the disease. The quoted sentences say what the papers report.
Hypertension (735 papers, 2007 to 2026). The presence of chronic increased pressure in the systemic arterial system. "The angiotensin receptor type I gene (AGTR1), responsible for encoding angiotensin receptor type 1 (AT1R), was found in the subgroup with an unspecified hypertension phenotype." (PMID 40004206, 2025). "The genetic variants of ACE and AGTR1 can be justifiably considered candidate genes related to the pathogenesis of hypertension in diabetes." (PMID 40149592, 2025). "AGTR1 polymorphism has been connected with essential hypertension, LVH, myocardial infarction, and DN when associated with poor glycemic control." (PMID 40149592, 2025). "The rs5182 polymorphism (C573T) of AGTR1 alters AGTR1 expression and is related to the presence of diabetes combined with hypertension in the Han population of Inner Mongolia." (PMID 39080710, 2024). "Previous meta-analyses confirmed the association of the AGTR1 A1166C polymorphism with coronary heart disease and essential hypertension." (PMID 38166133, 2024). "In a case control study, A44221G of AGTR1 was shown to be associated with hypertension in African Americans in a single-locus analysis with the G allele increasing hypertension risk." (PMID 36329155, 2023). "Rs5186 in AGTR1 is related to different therapeutic efficacy to CCBs and ACEIs in 311 White Europeans with hypertension whereas associated with ARBs on systolic blood pressure (SBP) response in 1,049 Chinese patients with hypertension." (PMID 36950018, 2023). "Upon receptor-mediated endocytosis of angiotensin II from AGTR1, vasoconstriction leads to hypertension, contributing to neuronal injury, which causes neurodegeneration associated with PD and Alzheimer’s disease." (PMID 37686360, 2023). "Many experimental studies have indicated that puerarin can cause a reduction of AGTR1 expression in hypertension animal models." (PMID 36046450, 2022). "This indicates that AGTR1 gene polymorphism is involved in the arterial stiffness of hypertension patients, which is consistent with the present study." (PMID 36577936, 2022). "In terms of AGTR1 polymorphism, AC + CC genotype significantly increased the control rate of hypertension in patients with valsartan treatment compared to the AA genotype (AC + CC vs. AA: OR 2.988, 95% CI 1.340–6.661, P = 0.007)." (PMID 35345577, 2022). "This study showed that the GG genotype of the AGTR1 gene was the most common genotype in patients with hypertension and LVH, and the distribution of AGTR1 polymorphisms was significantly different in the LVH and non-LVH patients." (PMID 36577936, 2022). "Previous studies have shown that AGTR1 A1166C is implicated in the hypertension risk and the sensitivity of ARBs; however, the conclusion is unanimous." (PMID 35345577, 2022). "Angiotensin receptors and especially AGTR1 in the kidney have been reported to be primarily causative for hypertension in mammals and are associated with renal sodium handling." (PMID 35406662, 2022). "The rs5186 (A1166C) variant is located at the 3’untranlated region (3’UTR) of the AGTR1 gene, potentially can affect mRNA stability and, therefore, AGTR1 levels, and associated with increased risk of hypertension." (PMID 34805533, 2021). "Numerous studies have shown the association of AGTR1 gene 1166A>C (rs5186) polymorphism with arterial hypertension, vasoconstriction, and sodium retention in the body." (PMID 35126748, 2021). "Several studies have shown the association of AGTR1 (1166A>C, rs5186) gene polymorphism with hypertension, vasoconstriction, and sodium retention in the body." (PMID 35126748, 2021). "Protein levels of AGTR1 in untreated essential hypertension patients homozygous for the C allele of rs5186 were also favorably linked with systolic and diastolic blood pressure." (PMID 34925466, 2021). "The expression levels of miR-155 were also negatively linked with AGTR1 protein levels, and miRNA levels were lower in those with the CC genotype that is directly associated with hypertensions." (PMID 34925466, 2021).
Hypertension (continued). "As we all know, hypertension cases are insulin-resistant; AGTR1 polymorphism is also found to be associated with early inflammatory and metabolic changes in prehypertensive cases." (PMID 32382544, 2020). "SNPs in several other genes have also been shown to be associated with hypertension such as A1161 polymorphism in angiotensin II type I receptor gene (AGTR1) and CYP11B2 gene polymorphism." (PMID 31906879, 2020). "Previous genetic studies found that AGTR1 variants are associated with essential hypertension in Polish and Finnish populations." (PMID 31538912, 2020). "Results from the PPI analysis identified IL-8, JAK2, AGTR1, and BCR to be the centers of genomic changes, in which AGTR1 was the target of hypertension, the common cause of cardiac remodeling triggered by mechanical stress." (PMID 31772688, 2019). "Significant association of AGTR1 polymorphism with hypercholesterolemia was also observed in hypertension patients." (PMID 30736745, 2019). "Polymorphisms in AGTR1 associated with hypertension have been studied, but the results were inconsistent and conflicting." (PMID 28381821, 2017). "Several studies have also shown significant associations of AGTR1 gene rs5186 SNP on several types of NCDs such as hypertension and type II diabetes mellitus, including a systematic meta-analysis with coronary heart disease." (PMID 28792482, 2017). "Previous studies have shown that variants on genes including AGTR1 are associated with hypertension." (PMID 27756246, 2016). "At present, abundant data extensively implicates the AGTR1 rs5186 SNP as a risk factor for hypertension." (PMID 26910623, 2016). "Hsa-miR-155 is proposed to specifically target one allele of the type-1 angiotensin II receptor (AGTR1) gene, resulting in it’s under- expression, which contribute to a reduced risk of hypertension." (PMID 26062604, 2015). "In this case-control study, we examined possible associations between polymorphisms of the AGT, ACE, and AGTR1 genes and hypertension in the south Indian population age between 30 and 70 years." (PMID 24860821, 2014). "Polymorphisms in AGTR1 and especially the C allele of rs5186 (+1166A>C) have been associated with hypertension and the A allele of rs5186 has been associated with higher serum levels of high-sensitivity C-reactive protein (CRP) and inflammation." (PMID 23437094, 2013). "A decrease in ACE2 leads unambiguously to enhanced AngII action on AGTR1 and caused vasoconstriction and hypertension." (PMID 21298017, 2011). "Development of nephropathy is accelerated in the presence of hypertension and it is shown that the gene for AGTR1 may increase the risk of developing DN in patients with T1D through the effect on blood pressure." (PMID 39446857, 2024). "In the current study, we noted, for the A1166C AGTR1 polymorphism, that the presence of the AC heterozygote may reduce the risk of HF (after adjusted for age, gender, BMI, smoking, DM, and hypertension)." (PMID 35886041, 2022). "While existing studies suggested that the AGTR1 polymorphism is closely associated with hypertension, it remains unclear whether its genotype is associated with LVH and arterial stiffness." (PMID 36577936, 2022). "After adjustment for demographic and environmental factors, the CC + AC genotype of AGTR1 A1166C was markedly linked to better hypertension control with valsartan treatment compared to the AA genotype (odds ratio: 2.836, 95% confidence interval: 1.199–6.705, P = 0.018)." (PMID 35345577, 2022). "Besides its role in the regulation of blood pressure, AGTR1 is associated with various pathological conditions such as hypertension and diabetic nephropathy." (PMID 35203286, 2022). "Furthermore, the meta-analysis showed that the C allele and AC genotype of AGTR1 was associated with an increased risk of essential hypertension, while a decreased risk of essential hypertension was observed in the A allele and AA genotype." (PMID 35886041, 2022).
Hypertension (continued). "They discovered that miRNA miR-155 could bind to the A allele of the SNP rs5186 (A>C) in the 3′UTR of the AGTR1 mRNA more efficiently than the C allele (which is more common in essential hypertension)." (PMID 34925466, 2021). "Indeed, a single-nucleotide-polymorphism (rs5186) disrupts the binding site for miR-155-5p in the type 1 angiotensin II receptor (AGTR1) mRNA and is associated with increased risk for hypertension." (PMID 32733281, 2020). "A study investigating the association of AGTR1 promoter methylation with the risk of essential hypertension showed that CpG1 hypomethylation in the AGTR1 promoter is likely associated with the risk of essential hypertension, with significantly lower CpG1 methylation levels in males than in females." (PMID 31538912, 2020). "Polymorphisms of AGTR1 such as rs5186 are associated with hypertension." (PMID 31511791, 2019). "The association of the AGTR1 gene with advanced head and neck cancer is important because it identifies an additional target for chemotherapy as there are several different blocking agents already in use for the treatment of hypertension." (PMID 29371888, 2018). "Studies have shown that A/C transversion at position 1166 in the 3′ untranslated region of the AGTR1 gene could be associated with hypertension." (PMID 28903744, 2017). "Altered expression of AGTR1 may cause decreased systemic expression, which may result in lower prevalence of hypertension." (PMID 27240348, 2016). "Significant association between AGTR1 rs5182 and hypertension was also found in Mexican population." (PMID 27240348, 2016). "The (−535) T allele of AGTR1 is believed to increase hypertension risk among African Americans." (PMID 27756246, 2016). "Furthermore, increased frequency of a SNP at 1166 position (A/C transversion) in the 3′ UTR of AGTR1 has been associated with hypertension, cardiac hypertrophy, myocardial infarction and increased oxidative stress levels in human heart failure." (PMID 25981295, 2015). "AGTR1 has been associated with hypertension, leading to a hypothesis that lower blood pressure in patients with trisomy 21 could be partially caused by the overexpression of miR-155." (PMID 25606462, 2014). "The current study showed that the polymorphism AGTR1 A1166 C was significantly related to the antihypertensive effect of valsartan, suggesting that the C allele of AGTR1 is an independent factor associated with better control of hypertension under valsartan treatment." (PMID 35345577, 2022). "The A→C polymorphism within the miR-155 binding site within the 3′ UTR of AGTR1 (Angiotensin II type 1 receptor) mRNA is responsible for a reduced binding of inhibitory miR-155 leading to an increased level of AGTR1 protein which is associated with hypertension." (PMID 23896598, 2013). "In the presence of cumulative doses of Ang II, the vasocontractile response was greater in mesenteric artery segments of T-treated dams, suggesting that T induces hypertension in pregnant rats via angiotensin II receptor type 1 (AGTR1)." (PMID 38534724, 2024). "Conversely, the AGT rs5051 GT, AGTR1 rs5186 AC and CC, and AGT rs699 CC genotypes resulted in an increased risk of developing hypertension, with odds ratios of 2.7688, 2.9494, 63.3178, and 10.6507, respectively." (PMID 38541065, 2024). "Five variants (CYP11B2 rs179998, AGT rs5051 and rs699, AGTR1 rs5186, and ACE rs4646994) were significantly associated with essential hypertension in the cohort under study." (PMID 38541065, 2024). "ACE inhibitors and AGTR1 antagonists are these days indispensable in the management of hypertension and blood pressure." (PMID 37445727, 2023). "Losartan, an antagonist of the angiotensin II receptor, type 1 (AGTR1), is used for hypertension treatment." (PMID 38414974, 2023).